MRPS18B (mitochondrial ribosomal protein S18B)
Synonyms: MRP-S18-2; C6orf14; HSPC183; PTD017; MRPS18-2; mS40; HumanS18a; S18amt
Tractability: Small molecule: a structure with a bound ligand is known. PROTAC: ubiquitination databases record sites on it; its protein half-life has been measured.
Target class: Other cytosolic protein
Gene: Protein-coding gene on chromosome 6 (30,617,823 to 30,626,398, forward strand). Ensembl gene ENSG00000204568.
Subcellular location: Mitochondrion
Subcellular location (Human Protein Atlas): Mitochondria; Cell Junctions
Pathways (Reactome):
Metabolism of proteins: Mitochondrial ribosome-associated quality control; Mitochondrial translation elongation; Mitochondrial translation initiation; Mitochondrial translation termination
Gene Ontology:
Molecular function: protein binding; structural constituent of ribosome
Biological process: mitochondrial translation; translation
Cellular component: mitochondrial small ribosomal subunit; mitochondrion; mitochondrial inner membrane; ribosome
Genetic constraint (gnomAD): Loss-of-function variants: 28 observed, 34.41 expected, observed/expected ratio (o/e) 0.81, 90% interval 0.6 to 1.12. The upper end of that interval is the gene's LOEUF score, 1.12, which puts it in group 4 of 6, group 1 being the genes least tolerant of losing a copy. Missense variants: 343 observed, 354.72 expected, observed/expected ratio (o/e) 0.97, 90% interval 0.88 to 1.06. Synonymous variants: 118 observed, 129.91 expected, observed/expected ratio (o/e) 0.91, 90% interval 0.78 to 1.06.
Homologues: Orthologues: chimpanzee MRPS18B (99% identical), macaque MRPS18B (93% identical), pig MRPS18B (84% identical), dog MRPS18B (84% identical), guinea pig MRPS18B (78% identical), mouse Mrps18b (77% identical), rat Mrps18b (77% identical), zebrafish mrps18b (40% identical), Drosophila melanogaster mRpS18B (28% identical), Caenorhabditis elegans mrps-18B (21% identical).
Diseases named in the same sentence as MRPS18B in open-access papers:
MRPS18B is named in the same sentence as 14 diseases in open-access papers, as found by Europe PMC text mining. Sharing a sentence is not in itself a finding about the gene and the disease. The quoted sentences say what the papers report.
endometrial cancer (3 papers, 2016 to 2024). Primary or metastatic malignant neoplasm involving the endometrium (mucous membrane that lines the endometrial cavity). "In mouse endometrial cancer xenografts, MRPS18B overexpressing cells produced larger and more vascularised tumours, suggesting high expression increases proliferation and tumour aggressiveness in vivo." (PMID 39354291, 2024).
Blindness (1 paper, 2021). Blindness is the condition of lacking visual perception defined as a profound reduction in visual perception. "For example, MRPL2, MRPL14, MRPS10, MRPS18A, and MRPS18B are candidate genes for spinocerebellar ataxia with blindness and deafness." (PMID 34987545, 2021).
breast carcinoma (1 paper, 2024). "In breast cancer, pathway enrichment analysis found that MRPS18B had roles in cancer-associated pathways including PIP3/AKT, oestrogen signalling, cell cycle, and circadian rhythm, however functional studies are needed to understand how MRPS18B impacts these pathways." (PMID 39354291, 2024).
cardiomyopathy (1 paper, 2022). A disease of the heart muscle or myocardium proper. "Several of them are associated with cardiomyopathy, as was also observed in a study by our group where the presence of a different mutation in the MRPS18B gene was identified in CCC patients." (PMID 36140315, 2022).
Chagas disease (1 paper, 2022). A parasitic infection caused by Trypanosoma cruzi. "In this work, we focused on evaluating the impact of variants of MRPS18B, because recent studies link mitochondrial dysfunction and poor prognosis of Chagas disease." (PMID 36140315, 2022).
prostate carcinoma (1 paper, 2024). A carcinoma that arises from epithelial cells of the prostate gland. "An increase in MRPS18B expression is also associated with EMT and metastatic capacity in endometrial and prostate cancer." (PMID 39354291, 2024). "The same study also found that increased expression of MRPS18B improved the migratory ability of prostate cancer cells through the induction of EMT, via chemokine signalling (CXCL12-CXCR4), and increased EMT transcription factor (TWIST2) expression." (PMID 39354291, 2024). "Whereas, using a prostate cancer zebrafish xenograft model, experimental fish developed smaller tumours that migrated faster compared to those microinjected with low MRPS18B expressing cells." (PMID 39354291, 2024).
renal carcinoma (1 paper, 2017). A carcinoma arising from the epithelium of the renal parenchyma or the renal pelvis. "Recently, a study of overexpression of Mrps18b in human breast and renal cancer cell lines has shown that Mrps18b results in the appearance of multinucleated cells." (PMID 28056857, 2017).
cancer (2 papers, 2018 to 2024). A tumor composed of atypical neoplastic, often pleomorphic cells that invade other tissues. "Comparatively, MRPS18B has been associated with more than one cancer type." (PMID 39354291, 2024). "Furthermore, there is compelling emerging evidence that increased MRPS12, MRPS16 and MRPS18B expression and association with metastatic capacity are observed across five different cancer types, collectively." (PMID 39354291, 2024). "The potential use as a biomarker of advanced disease requires larger cohort studies to understand the extent to which MRPS18B contributes to cancer progression, more broadly." (PMID 39354291, 2024).
MRPS18B also shares sentences with these, for which no sentence is quoted: deafness (1 paper); endometrial tumours (1); prostate tumor (1); pulmonary TB (1); spinocerebellar ataxia (1); tumour (1).